CRP (C-reactive protein)
Diseases named in the same sentence as CRP in open-access papers (continued):
Sharing a sentence is not in itself a finding about the gene and the disease.
infection (continued). "Changes in CRP and PCT over 2–7 days have been described in non-critically ill patient populations, in relatively small studies, about 50 patients or less, in specific conditions or in heterogeneous conditions in the ICU, to judge the course of infection and its sequelae." (PMID 23762396, 2013). "PCT levels were higher in patients with postoperative complications.PCT, but not CRP, levels correlated with APACHE, SOFA, lactate, duration of ECC, duration of surgery, and ICU stay.PCT: cut-off 2 ng/ml, sensitivity 83.3%, specificity 75.2% in predicting infections." (PMID 17038199, 2006). "However, conventional laboratory indicators such as CRP, PCT, and WBC are not sensitive or specific enough for diagnosing suppurative meningitis, further complicating early identification.The level of lactate dehydrogenase (LDH) indicates the severity of cell injury and increases with infection." (PMID 39026204, 2024). "However, other factors, such as age, sex, infection time, etiology, HbsAg, hepatitis B virus copies, alanine aminotransferase (ALT), aspartate aminotransferase, total bilirubin, prothrombin time, and AFP were all detected to have none apparent influence regarding serum Hs-CRP level (all P > 0.05)." (PMID 26656354, 2015).
cancer (2,403 papers, 1993 to 2026). A tumor composed of atypical neoplastic, often pleomorphic cells that invade other tissues. "The study also showed that CRP levels are associated with cancer-specific mortality in more advanced disease." (PMID 41546786, 2026). "Their findings suggest that individuals with consistently high or increasing CRP levels face a higher risk of developing cancer, reinforcing the importance of inflammation as a central factor in cancer risk and progression." (PMID 41554683, 2026). "Unadjusted competing-risk analysis revealed that CRP levels >2 mg/L conferred a 1.12-fold higher risk of cardiovascular death in cancer survivors compared to CRP ≤2 mg/L (sub-distribution hazard ratio [sHR]: 2.12; 95% CI: 1.40-3.21; P < 0.001)." (PMID 41579826, 2026). "Sensitivity analyses excluding cancer patients and early deaths minimized reverse causation, while CRP-adjusted models confirmed eGDR's independence from acute inflammation." (PMID 40959566, 2025). "While biomarkers albeit PD-L1 are scarce, declined performance status and cancer-related systemic inflammation detected by blood inflammatory markers such as C-reactive protein (CRP) have been linked to inferior prognosis." (PMID 40091413, 2025). "Elevated CRP, as an inflammatory marker, has been consistently linked to poorer prognosis in cancer patients." (PMID 40836295, 2025). "Both SII and CRP can be used to reflect the body’s inflammation level, and clinical studies have found that higher CRP potentially increases the risk of cancer mortality." (PMID 40129693, 2025). "Non-TB studies demonstrate that chronic inflammation (elevated IL-6 and CRP) is associated with increased cancer risk." (PMID 40475250, 2025). "This SH-SAW sensor demonstrated the capability to detect biological markers, including C-reactive protein (CRP), lipoprotein (a) (Lp(a)), and apolipoprotein B (ApoB), which are associated with inflammatory processes linked to cancer." (PMID 39996991, 2025). "In all cancer groups CRP was associated with patient BMI, in accordance with other studies in healthy and pathological populations." (PMID 41409302, 2025). "This diverges from studies in pancreatic g‐NENs and other cancers, where elevated acute‐phase proteins, such as CRP, have been linked to poor prognosis." (PMID 41466721, 2025). "The regression analysis showed that compared to the control group, cancer (OR: 1.77) and OPMDs (OR: 1.67) had a significant association with salivary CRP levels after adjusting for age and sex." (PMID 39851610, 2025). "One review reported individuals with elevated CRP levels had a higher overall risk of developing cancer compared to those with lower levels." (PMID 41367907, 2025). "Systemic inflammation is a well‐documented feature of cancer cachexia, with increased circulating levels of C‐reactive protein (CRP) associated with weight loss in cancer patients." (PMID 39764565, 2025). "Serum CRP significantly mediated the associations of vitamin C, 25(OH)D, β-carotene, lycopene, folate, and iron with all-cause, cancer, and cardiovascular mortality, except for the association between iron and cancer mortality." (PMID 40023976, 2025). "A systematic review and meta-analysis of 63 studies indicated that circulating TNF and CRP were associated with DepS in cancer patients." (PMID 40289959, 2025). "Cancer patients at high risk of thrombosis have elevated levels of biomarkers such as D-dimer, C-reactive protein (CRP), and TF, which are associated with increased risk." (PMID 40944099, 2025). "Increased CRP levels are commonly associated with infections (including PD), inflammation, injuries, pregnancy, and cancer." (PMID 40272186, 2025). "Other clinically relevant indicators, sometimes associated with malignant neoplasms, include C-Reactive Protein (CRP) and Creatine Kinase-MB (CK-MB)." (PMID 40862934, 2025). "In cancer screening paradigms, CRP levels exhibit a dose-dependent association with malignant transformation risk." (PMID 40563367, 2025).
cancer (continued). "While elevated hs-CRP levels have been linked to cancer and cardiovascular risk, evidence for a causal relationship between CRP and these diseases remains limited." (PMID 40004724, 2025). "The association between elevated tumour markers and CRP levels in adenocarcinoma patients suggests a close relationship between inflammation and cancer progression." (PMID 40332145, 2025). "We determined the association of serum CRP levels with night sleep, considering survival time among terminally ill patients with cancer admitted to a palliative care unit." (PMID 41302347, 2025). "Elevated CRP levels indicate systemic inflammation, which is commonly associated with advanced stages of cancer due to the inflammatory response elicited by the tumor and the surrounding tissue." (PMID 40791284, 2025). "For example, CRP mediated 5.3 %, 4.5 %, and 3.3 % of the association of serum 25(OH)D with all-cause, cancer, and cardiovascular mortality, respectively." (PMID 40023976, 2025). "Site-specific meta-analyses also show that elevated CRP is significantly associated with increased risks of breast, colorectal, lung, and other cancers." (PMID 41367907, 2025). "Future studies should evaluate the role of IL-6 and CRP in risk stratification for TB associated cancer." (PMID 40475250, 2025). "C-reactive protein (CRP), a key player in the innate immune response, is implicated in various biological events related to cancer progression." (PMID 40420174, 2025). "PhenoAge includes inflammatory markers (C-reactive protein) and red blood cell indices, which are strongly linked to cancer and other chronic diseases." (PMID 40061382, 2025). "Cancer risk increases in a CRP-concentration-dependent manner, with progressive elevation of systemic CRP levels associated with heightened malignant potential." (PMID 40563367, 2025). "Patients with later-stage cancer, low/normal lymphocyte and platelet counts, and elevated C-reactive protein (CRP) levels also had a higher risk of all-cause mortality." (PMID 40361463, 2025). "This association is reinforced by both observational studies and Mendelian randomization studies, which demonstrate that elevated levels of CRP correlate with an increased risk of cancer." (PMID 39361532, 2025). "Logistic regression models were constructed to examine associations between oral frailty, dysgeusia, and weight loss, adjusting stepwise for performance status, C-reactive protein, sex, and cancer stage." (PMID 41372876, 2025). "The results of our study demonstrated a diagnostic cut-off value of >0.67 ng/mL of salivary CRP for differentiating cases (OPMDs + cancer) from the normal controls." (PMID 39851610, 2025). "High CRP and low albumin levels are markers of inflammation and disease burden, especially in cancer, and are associated with poor prognosis." (PMID 40124502, 2025). "A large-scale prospective cohort study revealed that elevated baseline CRP levels were associated with an increased risk of subsequent cancer development." (PMID 41586228, 2025). "In cancer, elevated CS levels have been associated with high CRP and metalloproteinase expression in the pleural effusions of patients with certain malignancies." (PMID 41614767, 2025). "The growing researches suggested that elevated levels of CRP are strongly associated with the risk of metabolic disease, cardiovascular disease, and certain cancers." (PMID 41179881, 2025). "IL-6 also drives other inflammatory factors (e.g., C-reactive protein) that are pertinent risk factors for diseases and conditions, including cancer and lower-back pain." (PMID 40740426, 2025). "This apparent paradox highlights the complexity of separating causal inflammatory effects from confounding relationships with underlying metabolic and systemic processes that simultaneously influence CRP levels and cancer risk." (PMID 41555998, 2025).
cancer (continued). "Compared with subjects in the first (i.e., lowest) quartile of serum CRP, those in the fourth quartile exhibited a 57 % and 63 % elevated risk of cancer mortality and cardiovascular mortality, respectively." (PMID 40023976, 2025). "CRP, a pentameric protein synthesized by the liver in response to IL-6 during inflammation, has been linked to vascular disease, respiratory issues, cancer, and increased mortality risk." (PMID 41403880, 2025). "Although systemic inflammation is a hallmark of cancer cachexia, 86% of cachectic patients in our cohort had CRP < 10 mg/L, indicating limited acute inflammation." (PMID 40906320, 2025). "Serum C-reactive protein significantly mediated 5.3%–20.4 %, 4.5%–18.1 %, and 3.3%–15.7 % of the associations of vitamin C, 25(OH)D, β-carotene, and lycopene with all-cause, cancer, and cardiovascular mortality, respectively." (PMID 40023976, 2025). "Conversely, serum CRP was positively associated with all-cause, cancer, and cardiovascular mortality (all p-trend across quartiles: ≤0.01)." (PMID 40023976, 2025). "In line with this, elevated CRP levels have been associated with increased cancer risk and poor prognosis in several malignancies." (PMID 40936914, 2025). "CRP levels are widely recognized as systemic inflammation biomarkers and have been associated with poorer cancer outcomes." (PMID 40420174, 2025). "Previous studies have indicated that reduced food intake, loss of appetite, and inflammation (measured as elevated C-reactive protein levels) are risk factors for overall survival in cancer patients." (PMID 40507149, 2025). "Elevated CRP concentrations have been linked with more progressed cancer stages as per the TNM classification, indicating a magnified inflammatory reaction within the disease state." (PMID 40034601, 2025). "The mediation effects of WBC count on the associations of vitamin C, β-carotene, lycopene, and iron with all-cause, cancer, and cardiovascular mortality were overall weaker than the corresponding mediation effects of serum CRP." (PMID 40023976, 2025). "A higher level of C-reactive protein, investigated in 19 studies, was also associated with cancer-related strokes, but a conclusive multivariate analysis was not performed." (PMID 39857281, 2025). "CRP, a pentraxin family protein released by hepatocytes in response to IL‐6, is a marker of increased cancer risk and worse prognosis." (PMID 40528380, 2025). "ARG1 expression was the most strongly associated with IL1A, NRG1, CCL1, and CRP in cancer str of the CRC tumors among the numerous associated genes (13 401 genes)." (PMID 38557819, 2024). "One possible explanation is that CRP causes angiogenesis to proceed more quickly in cancer patients by elevating their levels of angiogenesis factor and interleukin circulation." (PMID 38384810, 2024). "A high score in the modified Glasgow prognostic score (mGPS) is associated with poor prognosis in advanced cancer and utilises increased serum fibrinogen and CRP and decreased serum albumin levels, demonstrating the centrality of systemic inflammation." (PMID 38674936, 2024). "For instance, there have been identified associations between C-reactive protein (CRP) and fibrinogen levels and cancer incidence." (PMID 39314636, 2024). "Nowadays, the reasons why high CRP levels are associated with worse prognosis in cancer patients are still unclear and remain topics of debate." (PMID 39062127, 2024). "In contrast, our study found that high CRP levels is significantly associated with the incidence of COVID-19 pneumonia in cancer patients." (PMID 38215120, 2024). "Increased CRP levels have been associated with an increased risk of cancer as well as being a harbinger of poor prognosis for this disease." (PMID 39309742, 2024). "Older age, male sex, high serum CRP levels, and comorbidity with cancer have been reported as risk factors for early death, and are consistent with the clinical experience, which seems satisfactory." (PMID 38603695, 2024).
cancer (continued). "The serum CRP was associated with the incidence of Omicron variant COVID- 19 pneumonia in cancer patients." (PMID 38215120, 2024). "From our perspective, chronic inflammation, as reflected by elevated CRP, is often associated with worse prognosis in cancer patients, as it can drive tumor progression, immunosuppression, and metabolic dysregulation." (PMID 39682266, 2024). "This study aims to investigate the association between serum CRP and the incidence of COVID-19 pneumonia in cancer patients at the end of 2022 in China." (PMID 38215120, 2024). "The association between body mass index (BMI), CRP, and cancer risk has been explored through various Mendelian randomization studies." (PMID 39314636, 2024). "The association between CRP level and cancer-specific survival was analysed in both patient cohorts." (PMID 39613865, 2024). "Chronic inflammation is one of the major predisposing factors in cancer progression and is indicated by increased plasma levels of C-reactive protein (CRP), interleukin 6, and tumor necrosis factor-alpha." (PMID 38509114, 2024). "Elevated serum CRP levels have been observed in patients with numerous malignancies, highlighting a close association between inflammation and cancer." (PMID 39001318, 2024). "To further elucidate the impact of the combined exposure on cancer risk, we conducted a joint analysis based on the reference cutoff values of baseline CRP and MetS-Z levels in the participants." (PMID 38386717, 2024). "This study is the first cross-sectional study analyzing the association between serum CRP in cancer patients and Omicron variant COVID-19 pneumonia since the change in prevention and control policy of China." (PMID 38215120, 2024). "Another study showed that IL-6 is more strongly associated with all-cause mortality and cancer-related mortality, whereas CRP only primarily predicts cardiovascular mortality over a 16-year follow-up period." (PMID 39589972, 2024). "The presence of inflammatory serum proteins, such as CRP, can hence be employed in the diagnosis of cancer-associated cachexia." (PMID 39596015, 2024). "As in previous studies, the C-reactive protein (CRP) was found to be associated with increased risk of cancer, although with a marginal effect: hazard ratio (HR) = 1.02, 95% CI 1.00–1.04, p = 0.035." (PMID 38308367, 2024). "In a prior meta-analysis, the relationship between inflammation levels, as indicated by CRP, and the overall risk of cancer was thoroughly examined." (PMID 39314636, 2024). "High baseline CRP levels in healthy individuals are linked to increased future cancer risk, making CRP a potential biomarker for cancer risk and progression." (PMID 39498386, 2024). "In conclusion, this study found that cancer patients with higher serum CRP were more likely to suffering Omicron variant COVID- 19 pneumonia." (PMID 38215120, 2024). "Higher CRP has been shown to be associated with a worse prognosis in patients with various cancers compared to those with normal CRP." (PMID 39594844, 2024). "On the other hand, healthy patients with elevated CRP levels were associated with increased future risk of cancer." (PMID 39001318, 2024). "An elevation in serum CRP is observed in malignant tumors and is associated with several mechanisms leading to worse prognosis of tumor patients." (PMID 38877146, 2024). "CRP is a well-accepted marker of cancer-induced inflammation, associated with cancer cell proliferation, angiogenesis, and the inhibition of adaptive immunity." (PMID 39289234, 2024). "Numerous studies have reported that elevated systemic inflammation signified by increased levels of IL‐6, TNF‐α, and CRP contributes to cancer cachexia and is associated with poor survival." (PMID 38725139, 2024). "Reduced sleep in cancer patients was associated with elevated levels of CRP and interleukin-6 (IL-6), leading to an increase in the body's inflammatory levels." (PMID 39592977, 2024).